CLPP (caseinolytic mitochondrial matrix peptidase proteolytic subunit)
Diseases named in the same sentence as CLPP in open-access papers (continued):
Sharing a sentence is not in itself a finding about the gene and the disease.
cancer (continued). "The review highlights the therapeutic promise of ClpP agonists as a novel approach in cancer therapy, presenting their prospective potential for cancer treatment by focusing on an unexplored mitochondrial target." (PMID 40395852, 2025). "The novelty of this review is that it brings novel findings and potential anti-tumor drug targets for ClpP, so we can obtain safer and more effective anti-cancer drugs." (PMID 40395852, 2025). "To assess DRD2 and CLPP expression in human cancers, we verified the different expression for both genes across TCGA tumors by the TIMER database." (PMID 40699850, 2025). "ClpP emerges as a central regulator of multiple cancer-related processes, exerting its antitumor effects through the induction of mitochondrial stress, disruption of metabolic homeostasis, promotion of oxidative imbalance, and activation of apoptotic pathways." (PMID 41155556, 2025). "The observed mitochondrial protein degradation and cytotoxicity attributed to ONC201 is dependent on ClpP as knockdown of ClpP by siRNA protects multiple human cancer cell lines from ONC201-mediated cytotoxicity." (PMID 40145650, 2025). "Immunohistochemical staining of clinical specimens indicated that ClpP is expressed more highly in cancer cells than in para-cancerous tissues." (PMID 40395852, 2025). "Previously, researchers had identified functional crosstalk between LONP1 and ClpP, which are two mitochondrial matrix proteases that cooperate to attenuate proteotoxic stress and protect mitochondrial functions to promote cancer cell survival." (PMID 40083691, 2025). "In summary, ClpP and ClpX are stable and ubiquitously expressed to varying degrees in human healthy tissues and cancers, supporting their value as therapeutic targets in malignancies with heightened mitochondrial stress or metabolic vulnerability." (PMID 41155556, 2025). "The serine protease ClpP plays an important role in proteostasis, and more recently, ClpP has been found to be involved and over-expressed in various types of cancers." (PMID 40283959, 2025). "This specificity positions ZK53 as a more suitable candidate for assessing the potential of ClpP as a targeted therapeutic strategy in cancer, thereby minimizing the off-target effects and inherent unpredictability associated with polypharmacological agents." (PMID 41357605, 2025). "The selective activation of ClpP represents a novel and promising strategy in cancer therapy development." (PMID 41155556, 2025). "Represented by ONC201 and the TR compounds, small molecule ClpP activators (ClpP agonists) have generated considerable interest as anti-cancer agents with a novel mechanism of action." (PMID 41333384, 2025). "TR-57 and TR-107 were primarily evaluated in this study because they have been well characterized as selective ClpP activators with anti-cancer properties in TNBC." (PMID 41333384, 2025). "Although ClpP activators have promising antiproliferative and pro-apoptotic effects, their applicability is limited by the resistance of cancer cells." (PMID 39684886, 2024). "Drugs developed based on ClpP can achieve the ultimate goal of treating cancer by modulating ClpP activity." (PMID 39261452, 2024). "Here, we performed analysis of DRD2 and CLPP mRNA expression levels obtained from publicly available pediatric cancer transcriptomic data sets, established by St." (PMID 37589388, 2024). "Cancer cells are highly sensitive to chemical activation of ClpP, which does not induce death in normal cells despite a detectable degradation of ClpP substrate proteins." (PMID 39684886, 2024). "Inhibition of ClpP suppresses the proliferation, migration and invasion of cancer cells, which is manifested by a blocked cell cycle and a lower degree of metastasis." (PMID 39261452, 2024).
cancer (continued). "Several CLPP agonists (ONC201, as well as other imipridones) were demonstrated to be quite efficient against not only bulk tumor cells but also cancer stem cells, cancer-associated fibroblasts, and immune cells within the tumor microenvironment." (PMID 38397478, 2024). "The dysregulation of mitochondrial metabolic activity, protein level, and transcriptomic profiles in a wide variety of cancer cell models indicates the need to investigate the full scope of perturbations occurring in cancer cells following ClpP activation." (PMID 37063293, 2023). "It is not yet clear if these drugs reliably induce apoptosis in other cancer cells or if this is a common property of the anti-cancer response to ClpP agonists or POLRMT inhibitors." (PMID 37371693, 2023). "Ultimately, the determination of the protein substrates of activated ClpP will assist in a better understanding of the mechanism of action of ClpP-targeting compounds on cancer metabolism and growth." (PMID 37371693, 2023). "While this review aimed to emphasize the surprising similarities between these anti-cancer approaches, how ClpP agonists and POLRMT inhibitors compare to other mitochondria-targeting drugs also remains to be determined." (PMID 37371693, 2023). "Though progress has been made in identifying specific phenotypic outcomes following ClpP activation, the exact mechanism by which ClpP activation leads to broad anti-cancer activity has yet to be fully elucidated." (PMID 37063293, 2023). "Despite an incomplete understanding of the mechanism of action, ClpP agonists are currently under investigation as potential anti-cancer compounds due to their significant growth inhibitory effects on many different cancer cell lines and cancer models." (PMID 37371693, 2023). "There are a few known cancer cell mechanisms of resistance to ClpP agonists, including p0 cells, fumarate hydratase knockout cell lines, and ClpP knockout or ClpP mutant cell lines." (PMID 37371693, 2023). "Recent analysis of TCGA database also confirmed that ClpP is overexpressed in breast and other cancers." (PMID 37046596, 2023). "A synergistic effect of TRAIL and the ClpP agonist has been reported in breast and other cancer types." (PMID 37046596, 2023). "CLPP is an interesting drug target in cancer as inhibitors and activators have been identified and are candidate cancer drugs." (PMID 37508418, 2023). "The imipridone ONC201, a potent activator of the mitochondrial Clp protease proteolytic subunit (ClpP), was shown to inhibit cell proliferation and induce cell death in many cancers including GBM and one DMG patient." (PMID 37886173, 2023). "Additional studies need to be completed to determine if reliance on aerobic respiration is a key factor that influences the responsiveness of cancer cells to ClpP agonists or POLRMT inhibitors." (PMID 37371693, 2023). "This analysis shows a significantly higher transcript level of CLPP in primary tumors than in normal tissues, which indicates a safety window for small-molecule activators selectively targeting HsClpP in cancer cells." (PMID 37923710, 2023). "To gain a better understanding of the biological consequences of ClpP activation in cancer cells, we compared the effects of 2 well characterized ClpP activators in a model of TNBC." (PMID 37063293, 2023). "Clinical trial data report ClpP agonists to be well tolerated with minimal side effects in cancer patients, further suggesting a minor impact on normal cells." (PMID 37371693, 2023). "Most notably, ClpP agonists are known to impact a number of metabolic pathways that are required for cancer cell proliferation (i.e., proline biosynthesis and heme biosynthesis pathways)." (PMID 37371693, 2023). "In many types of human cancers, ClpP is overexpressed and is required to sustain oncogenesis and tumor metastasis." (PMID 35245501, 2022). "A previous study revealed that robust ClpP activity endows cancer cells with resistance to cisplatin." (PMID 35180892, 2022).
cancer (continued). "HSP60 regulated ClpP expression via c-Myc and physically interacted with ClpP to restore mitochondrial functions that promote cancer cell survival." (PMID 35653190, 2022). "It has shown that ClpP is universally overexpressed in primary and metastatic human cancer, correlating with poor patient survival." (PMID 36389399, 2022). "Previous studies have shown that ONC201 and its TR compound analogs, which belong to the imipridone class of small molecules, can specifically bind to ClpP, consequently inhibiting the proliferation of cancer cells." (PMID 35180892, 2022). "ClpP interacts with multiple respiratory chain proteins and metabolic enzymes in mitochondria that are essential for metabolic regulation in cancer cells." (PMID 35180892, 2022). "Cancer cells exploit the functions of ClpP and LONP1 in mitochondrial homeostasis and energy metabolism to accelerate their own invasion and metastasis." (PMID 35180892, 2022). "Together, these structural data are expected to aid ongoing drug design efforts that target the ClpP-ATPase complex in bacterial infections and cancers." (PMID 35245501, 2022). "ClpP has been found to be increased in several cancers including BC and its expression has been found to be associated with poor prognosis." (PMID 34441434, 2021). "Here, we identified the specific target substrates of each protease and discovered functional crosstalk through which LONP1 and ClpP cooperatively modulate aspects of mitochondrial proteostasis that are crucial for cancer cell growth and survival." (PMID 33637676, 2021). "To investigate relationships between the two proteases, we first analyzed patterns of LONP1 and ClpP expression in various cancer types from The Cancer Genome Atlas (TCGA) database." (PMID 33637676, 2021). "Considering these results, recent studies try to identify and characterize new molecules that can target and modulate ClpP activity to selectively kill cancer cells." (PMID 34207660, 2021). "Recent reports highlight the role of mitochondrial proteins Mitofusin-2 (Mfn2) and caseinolytic protease P (ClpP) in cancer progression." (PMID 34441434, 2021). "Accordingly, inhibition of both LONP1 and ClpP potently reduced cancer cell viability with concomitantly induced mitochondrial bioenergetics dysfunction as evidenced by phosphorylation of AMPK and activation of autophagy." (PMID 33637676, 2021). "Together, these findings further indicate a link between LONP1 and ClpP function in cancer cell proliferation and viability." (PMID 33637676, 2021). "In this study, we found evidence of functional crosstalk between LONP1 and ClpP within the mitochondrial protein quality control pathway required for cancer cell survival." (PMID 33637676, 2021). "Here, we demonstrated that LONP1 and ClpP work together to maintain mitochondrial proteostasis in cancer." (PMID 33637676, 2021). "In recent years, ClpP gained interest as an anticancer drug target, as it proved to be important for tumor proliferation in cancer types that have an increased dependence on mitochondrial function and thereby, high ClpP levels." (PMID 34109219, 2021). "Despite the same principle mechanism, the imipridones were much more potent than ADEP1 in activating human mitochondrial ClpP and in inhibiting the proliferation of cancer cells." (PMID 34109219, 2021). "Imipridone ONC201, a highly potent ClpP overactivator, is already in clinical trials for several cancers, further highlighting the enormous potential of ClpP as anticancer target." (PMID 34045646, 2021). "LONP1 and ClpP genes closely localized to chromosomal region 19 and were co-expressed at high levels in most human cancers." (PMID 33637676, 2021). "Mitochondrial protease ClpP was found overexpressed in a subset of hematological and solid tumors where it is necessary for cancer cell viability." (PMID 34888254, 2021).
cancer (continued). "In cancer cells, ClpP activation by ONC201 led to the degradation of respiratory chain subunits, impaired oxidative phosphorylation, and apoptosis." (PMID 34109219, 2021). "In our study, we found that SHMT2 is a common target substrate of LONP1 and ClpP for cancer cell survival." (PMID 33637676, 2021). "ONC201 treatment decreased oxidative phosphorylation through activation of ClpP to reduce basal oxygen consumption rate and enzymatic activity of respiratory chain complexes I, II, and IV in cancer cells." (PMID 33557912, 2021). "In summary, our study reveals a functional relationship between two mitochondrial proteases LONP1 and ClpP in maintaining mitochondrial proteostasis in cancer." (PMID 33637676, 2021). "In eukaryotic cells, it is encouraging that ClpP inhibition causes only a mild phenotype in most cell types while certain cancer subtypes with enhanced dependence on ClpP are highly sensitive." (PMID 34109219, 2021). "LONP1 and ClpP genes closely localized on chromosome 19 and were co-expressed at high levels in most human cancers." (PMID 33637676, 2021). "It is known that dependent on the type of malignancy, ClpP overexpression in human cancer correlates with low patient survival." (PMID 34045646, 2021). "Here, we identified functional crosstalk between LONP1 and ClpP, which are two mitochondrial matrix proteases that cooperate to attenuate proteotoxic stress and protect mitochondrial functions for cancer cell survival." (PMID 33637676, 2021). "As previously reported, many cancers showed increased expression levels of ClpP, and the silencing of this protease significantly impairs mitochondrial OXPHOS and inhibits cell proliferation." (PMID 34207660, 2021). "Although LONP1 and ClpP exert similar actions in cancer, their regulatory mechanisms and potential interconnections remain largely unexplored." (PMID 33637676, 2021). "The suppressive effect of ClpP silencing on cancer cell growth was confirmed by the colony formation assay." (PMID 32195060, 2020). "The extensive processing steps needed for CLPP maturation into an active form all represent potential mechanisms for the acquisition of resistance to imipridones or other CLPP activators by cancer cells." (PMID 32094149, 2020). "While fewer studies have examined the importance of ClpX for the viability of malignant cells, it is believed that the results with ClpP are a surrogate for the activity of the ClpXP holoenzyme and inhibiting ClpX in cancer would produce similar results." (PMID 33037181, 2020). "In cancer cells, expression of a constitutively active mutant CLPP induces cell death in vitro and in vivo." (PMID 32761807, 2020). "Pharmacological activation of mitochondrial CLPP by ADEP analogs can efficiently kill certain types of cancer cells." (PMID 32094149, 2020). "ClpP is a unique cancer target as both inhibition and hyperactivation kill malignant cells, although through different mechanisms." (PMID 33037181, 2020). "The anti-cancer activity of CLPP/VSVMP mRNA complex was first evaluated on C26 abdominal cavity metastases model by intraperitoneal administration." (PMID 35539419, 2018). "The CHOP axis of the UPRmt and its role in cancer biology has been recently addressed, mostly focusing on ClpP, the AAA+ peptidase subunit of the ClpXP, a complex that is induced by CHOP." (PMID 28798902, 2017). "ClpP is universally overexpressed in primary and metastatic human cancer, correlating with shortened patient survival." (PMID 27389535, 2016). "Immunohistochemical staining of a universal cancer tissue microarray demonstrated that ClpP was overexpressed in virtually every human malignancy examined, with intense cytoplasmic staining in the tumor cell population." (PMID 27389535, 2016). "As such, these studies may have important implications for potential treatments of this specific type of cancer with ClpP agonists." (PMID 41333384, 2025).
cancer (continued). "Moreover, the development of novel compounds based on diverse scaffolds will not only expand the repertoire of ClpP modulators but also provide deeper insights into the biology of ClpP and its context-dependent role in cancer." (PMID 41155556, 2025). "Recent studies have also explored the role of ClpP in cancer treatment." (PMID 40395852, 2025). "Cancer cells depend on ClpP for mitochondrial proteostasis, metabolic adaptation, and survival." (PMID 41155556, 2025). "Moreover, various cancer types respond differently to ClpP agonists, illustrating the need to better understand the specific effects of these anti-cancer compounds." (PMID 41333384, 2025). "ClpP was confirmed as a target of imipridones through crystallography and biochemical studies, and ClpP agonism was shown to induce selective lethality in cancer cells." (PMID 41008904, 2025). "Therefore, too low or too high levels of ClpP lead to cancer cell death through different mechanisms in different cancers." (PMID 39261452, 2024). "UM tumors showed high CLPP gene expression amongst the evaluated cancer types." (PMID 39394450, 2024). "The promising clinical benefits testing dordaviprone in clinical trials, expanded access schemes and through unorthodox routes, coupled with the identification of CLPP overexpression in aggressive cancers including DMG, has stimulated the development of new ClpP agonists called “TR” analogs." (PMID 37589388, 2024). "More aggressive cancer subtypes tended to express more CLPP mRNA than low-grade cancers." (PMID 37589388, 2024). "Comparing p0 cells to ClpP agonist- or POLRMT inhibitor-treated cells may help establish if the loss of mtDNA is a critical and common anti-cancer response to these treatments." (PMID 37371693, 2023). "Thus, our data further illustrates the high degree of specificity of these compounds for ClpP and confirm that this is the major target protein for these molecules in cancer cells." (PMID 37063293, 2023). "The current study utilized a comprehensive multi-omics approach to identify protein, transcript, and metabolite-level changes to further elucidate the specific mechanism of action of these compounds and identify potential cancer cell vulnerabilities resulting from ClpP activation." (PMID 37063293, 2023). "A remaining and important question is whether inhibition of POLRMT or activation of ClpP by small molecules results in the development of resistance in cancer cells." (PMID 37371693, 2023). "Interestingly, both inhibition and hyperactivation of ClpP can lead to impaired OxPhos, resulting in cancer cell death." (PMID 37046596, 2023). "Inability to sensitize or desensitize cells to ONC201 or TR-57 treatment could be due to ClpP activation broadly affecting a number of metabolic pathways in cancer cells." (PMID 37063293, 2023). "Results of these studies clearly indicate the importance of studying both ClpP and ClpX when treating cancer cells with imipridones because their diversified response is obviously dependent on the cell types as well as on different members of the imipridone family." (PMID 36675163, 2023). "In contrast, ClpP activation induces mitochondrial proteolysis and cancer cell lethality." (PMID 35653190, 2022). "Although its activation plays a crucial role in maintaining cancer cell proteostasis, the oncogenic effects of ClpP may be dose dependent." (PMID 35180892, 2022). "An independent report has further substantiated the role of ClpP in cancer." (PMID 36389399, 2022). "The scarcest insights came from a CLPP-substrate trapping study of Homo sapiens AML cancer cells." (PMID 35954215, 2022). "Cancer cells require increased protein synthesis to meet the demands of increased cellular proliferation, which, conceivably, will cause mitochondrial stress and activation of the UPRmt, leading to upregulated synthesis of HSP60 and ClpP." (PMID 35653190, 2022).